EGFR (epidermal growth factor receptor)
Diseases named in the same sentence as EGFR in open-access papers (continued):
Sharing a sentence is not in itself a finding about the gene and the disease.
lung cancer (continued). "In recent years, more attention has been paid to the relationship between EGFR and the development of lung carcinoma, and EGFR-TKIs targeting EGFR have been widely applied for the treatment of advanced lung carcinoma." (PMID 34738874, 2022). "EGFR was found in microvesicles (MVs) from the human cancer cell line A431 (skin epidermoid carcinoma), as well as from A459 (lung carcinoma) and DLD-1 (colorectal carcinoma) cell lines." (PMID 35158999, 2022). "We topically applied Rosi gel to nude mice subcutaneously receiving PC9 lung carcinoma cells, for which EGFR inhibitors are approved for first-line treatment." (PMID 35324426, 2022). "EGFR mutations, ALK rearrangements and ROS1 rearrangements are regarded as “must test” biomarkers in the molecular diagnosis of advanced lung carcinoma patients." (PMID 35031014, 2022). "HER2 mutations mainly occur at exon 20 in the protein kinase domain and are recognized as primary drivers in lung cancer, similar to other oncogenic drivers, such as EGFR, ROS, ALK, KRAS and BRAF." (PMID 33959501, 2021). "This is in line with recent work on advanced lung cancer, for which sMET was suggested to act as a dynamic monitoring marker of EGFR‐TKI treatment." (PMID 33690968, 2021). "EGFR-tyrosine kinase inhibitors (EGFR-TKIs) are used successfully as targeted therapies in lungs cancer." (PMID 34790566, 2021). "The advancements in molecular profiling in lung cancer have provided powerful tools for implementing new treatments, such as EGFR and ALK tyrosine kinase inhibitors." (PMID 33956842, 2021). "RUSC2 interacts with the SHD domain of GIT2 and reduces GIT2 degradation, which regulates lung cancer progression through EGFR signaling." (PMID 34642262, 2021). "Despite the progress of advanced target therapeutic agents and immune checkpoint inhibitors, EGFR‐TKI resistance is still one of the biggest obstacles in treating lung cancer." (PMID 33486901, 2021). "For instance, the discovery of tyrosine kinase inhibitors targeting mutant epidermal growth factor receptor (EGFR) has provided a good example of lung cancer target therapy." (PMID 34439260, 2021). "With the deepening of the world's tumor molecular biology research, lung cancer targeted therapy has made outstanding achievements, especially the EGFR-TKIs, which has significantly improved the life cycle of lung cancer patients in the past 10 years." (PMID 34222178, 2021). "In this study, we focused on the association of ANXA1 and chemosensitivity with a third generation epidermal growth factor receptor-tyrosine kinase inhibitor (EGFR-TKI), Osimertinib, in lung cancer cells with EGFR mutations." (PMID 34439260, 2021). "Several mechanisms have been proposed, such as stress-activated p38 being able to directly phosphorylate EGFR on Ser1015 in lung cancer cells." (PMID 34831480, 2021). "Relative effect of the de novo vs. secondary setting, compared to the effect of metastatic pattern and ECOG performance status on overall survival of EGFR+ lung cancer patients." (PMID 33898315, 2021). "In lung cancer, intercellular communication through exosomes has been found to contribute to the resistance of EGFR-TKI and anti-angiogenesis therapy." (PMID 34680445, 2021). "Further study showed that the knockdown of ANXA1 inhibited the phosphorylation of EGFR and down-stream Akt pathways and promoted apoptosis in lung cancer cells treated with Osimertinib." (PMID 34439260, 2021). "HOTAIR has been shown to be suppressed in EGFR-TKI-resistant lung cancer cell lines and tissues, while HOTAIR transfectants restored sensitivity to EGFR-TKIs." (PMID 34692550, 2021). "Cell experiments have shown that 68 has an effect on cardiac fibroblasts (CFs) and RAW264.7 macrophages and can be used as a potential dual inhibitor of EGFR and ATX in the treatment of pulmonary fibrosis caused by lung cancer." (PMID 34832985, 2021).
lung cancer (continued). "Based on the TCGA database, we found that the expression levels of PD-L1 in EGFR-mutant lung cancer were significantly increased compared with wild-type EGFR one." (PMID 33994852, 2021). "MET exon 14 is more frequently found in older patients than in patients with EGFR- or KRAS-mutant lung cancer." (PMID 34660325, 2021). "With the increase in the number of checkpoint inhibitor-based clinical trials being conducted, interest in integrating immunotherapy for patients with EGFR-mutant type (EGFR-MT) lung cancer has also increased." (PMID 34663810, 2021). "This study expands our knowledge of EGFR/RAS signaling in lung cancer and provides a genome-wide discovery of factors that cooperate with or antagonize oncogenic RIT1." (PMID 34373451, 2021). "More COPD, poor ECOG PS, and more liver metastases in underweight lung cancer were only noted in EGFR mutant patients." (PMID 34836017, 2021). "More than 55 additional clinical lung cancer samples, including small cell lung cancer, multiple primary lung cancer, and EGFR-TKIs resistant lung cancers, are being constructed as PDX models in our laboratory." (PMID 33628593, 2021). "In another study, activation of EGFR led to decreased protein levels of DSC3, whereas EGFR inhibition resulted in enhanced expression of DSC3, indicating an EGFR-dependent regulation of DSC3 in lung cancer." (PMID 34527572, 2021). "Since the RI value of genistein is better than that of volasertib, we sought to investigate the effects of EGFR in paclitaxel-resistant lung cancer." (PMID 34503223, 2021). "For instance, declines in circulating allele fractions of relevant mutations have been associated with clinical outcomes in melanoma, colorectal cancer, breast and ovarian cancer, and EGFR-positive lung cancer." (PMID 34298813, 2021). "Osimertinib, a third-generation, irreversible EGFR TKI, has become a standard of care first-line treatment for patients with EGFR-mutant lung cancers." (PMID 34140482, 2021). "Targeted delivery of EV‐encapsulated PTX at a low dose (10‐20 times lower than the clinical‐equivalent dose) significantly enhanced the drug efficacy in suppressing tumour growth in an EGFR‐positive lung cancer xenografted mouse model." (PMID 33643546, 2021). "Another recent study revealed that intragenic complex rearrangements were related to RB1 inactivation in EGFR-mutant lung cancer cell." (PMID 34271921, 2021). "Results have demonstrated, though, that as the treatment time increases, lung cancer tumors commonly develop resistance to EGFR‐TKIs." (PMID 33931980, 2021). "The clinical efficacy of epidermal growth factor receptor (EGFR)–targeted therapy in EGFR-mutant non–small cell lung cancer is limited by the development of drug resistance." (PMID 34516823, 2021). "For the EGFR heterogeneity in lung cancer, recent reports have indicated that tumors are composed of mixed populations of mutant EGFR and wild-type EGFR cells, suggesting that the intratumor heterogeneity does indeed exist." (PMID 34692766, 2021). "MET amplification in EGFR-mutant lung cancer was first described in an in vitro selected drug-resistant cell line and subsequently established as a clinical marker of EGFR TKI resistance in patients." (PMID 34516823, 2021). "Genetic alterations and concurrent alterations of c-MET/EGFR with other genetic alterations have been well reported in lung cancer, but were underreported in other solid cancers especially CRC, and hence our study is significant in this regard." (PMID 34512327, 2021). "In some lung cancer patients, CDKN2A deletion and EGFR mutation are coexistent to mediate poor drug response." (PMID 33959491, 2021).
lung cancer (continued). "EGFR mutation or amplification are frequently detected in lung cancer; and studies suggest that activation of TGF-β pathway is associated with EGFRi/EGFR tyrosine kinase inhibitor (TKI)/cetuximab resistance." (PMID 34917620, 2021). "We observe significant variability to epidermal growth factor receptor (EGFR) inhibition among and within multiple versions and clonal sublines of PC9, a commonly used EGFR mutant nonsmall cell lung cancer (NSCLC) cell line." (PMID 34061819, 2021). "The WJOG8815L phase II clinical study involves patients with non‐small cell lung cancer (NSCLC) that harbored the EGFR T790M mutation, which confers resistance to EGFR tyrosine kinase inhibitors (TKIs)." (PMID 33131198, 2021). "In particular, in lung cancer, genetic mutations in ALK, BRAF, EGFR, and ROS1 guide treatment decisions in patients affected by advanced disease and recurrence." (PMID 33959797, 2021). "Using an RNA interference screen, they identified that knockdown of FAS and NF-κB pathway components enhanced cell death in EGFR-mutant lung cancer cells treated with EGFR TKI erlotinib." (PMID 34071428, 2021). "An important question that remains unanswered by this study is the mechanism(s) accounting for the range of EGFR TKI-induced innate immune responses observed in lung cancer cell lines and primary EGFR mutant lung tumors." (PMID 34001994, 2021). "Here, we investigated the potentials and mechanisms of action of Ashwagandha derived two steroidal lactone bioactive withanolides, Withanone (Wi-N) and Withaferin-A (Wi-A), for treatment of aberrant EGFR-derived lung cancers." (PMID 33530424, 2021). "Suppressed immunoproteasome and autophagy cascades that are known to influence antigen processing and presentation are likely drivers of immune evasion mechanisms in EGFR mutant lung cancer." (PMID 34638461, 2021). "Testing on EGFR localized to exosome membranes has been performed to evaluate its potential as a marker for diagnosing lung cancer." (PMID 33855679, 2021). "In our study, we measured the frequency of EGFR and ALK concurrent mutations associated with lung cancer, and studied the responses to TKI treatment in this rare patient population." (PMID 34654390, 2021). "For lung cancer cells, PD-L1 expression was impaired after EGFR tyrosine kinase inhibitor (TKI) treatment." (PMID 33413496, 2021). "The novel nanohybrid was observed to induce significant apoptosis in EGFR-positive lung cancer cells by suppression of autophagic mechanisms." (PMID 34138386, 2021). "Since the discovery of EGFR overexpression in patients with lung cancer, which revealed a correlation between EGFR tyrosine kinase expression and tumor formation, numerous agents with significant therapeutic targets in NSCLC have been developed." (PMID 34393769, 2021). "Over the most recent decade, the discovery of targeted therapeutic agents, EGFR tyrosine kinase inhibitors (TKIs), has revolutionized the treatment of lung cancer." (PMID 34885115, 2021). "EGFR, KRAS, and PIK3CA gene mutations have a correlation with the clinical characteristics of lung cancer patients, which should be further accepted and improved to enhance the efficacy for personalized cancer treatment." (PMID 34217313, 2021). "In summary, we performed multivariate analyses using a cohort of patients who had undergone complete surgical resection for lung cancer to compare postoperative RFS between groups categorized according to their PD-L1 expression and EGFR mutation status." (PMID 34471191, 2021). "We have reported that cell detachment upregulates NADPH oxidase 4 (NOX4), which maintains EGFR levels and activities that are important for anoikis resistance in human lung cancer cells." (PMID 33440835, 2021). "EGFR and KRAS mutation characteristics in patients with lung cancer from Xuanwei/Qujing in previous studies." (PMID 33928034, 2021).
lung cancer (continued). "Suppression of miR-19b expression in EGFR mutant lung cancer cells has led to re phosphorylation of ERK, AKT and STAT and effector proteins." (PMID 34367998, 2021). "The present study offers a rationale to propose EGFR and MET inhibitors always in combination to patients with lung cancer harboring EGFR mutations and MET amplification." (PMID 34298655, 2021). "At present, the main targets of lung cancer targeted drugs that have been marketed and under development at home and abroad include epidermal growth factor receptor (EGFR) (HER1/ERBB1), HER2, MET, ROS1, VEGF, VEGFR2, and ALK5–10." (PMID 34059647, 2021). "In patients in the advanced stages of lung cancer, finding target molecules, such as EGFR, ALK, and ROS1, is significant for making treatment decisions; as such, it is necessary to perform molecular testing at the time of initial diagnosis." (PMID 34441366, 2021). "Consistent trends were found in other studies, and notably, EGFR inhibitors exhibited better performance in treating female patients with lung cancer than male patients." (PMID 33391446, 2021). "For example, we observed that eRNAs chr12.51786511.51786834 and chr7.55132578.55133258 were upregulated and located near GALNT6 and EGFR, which have been found to promote metastasis of lung cancer cells." (PMID 34439379, 2021). "Our analysis of this real-world cohort suggests that earlier access to a molecular diagnosis of EGFR-related lung cancer is expected to decrease complications and hospitalizations related to delays in initiation of therapy and avoid early deaths." (PMID 33652831, 2021). "The in vitro and xenograft studies indicate that osimertinib induced an IFN response that exhibits variation in both kinetics and magnitude among distinct EGFR mutant lung cancer cell lines." (PMID 34001994, 2021). "A recent study demonstrated that enhanced glycolysis by oncogenic EGFR supports the survival of lung cancer cells by inhibiting EGFR degradation, and that impairment of this system leads to apoptosis via JNK activation." (PMID 33677467, 2021). "Ectopic expression of TET1 effectively inhibits the growth of the lung cancer, while knockdown of TET1 causes lung adenocarcinoma cells to develop resistance to EGFR inhibitors." (PMID 34656178, 2021). "Seleno-L-methionine (SeMet) reduced EGFR transcription and protein stability in human lung cancer cell lines." (PMID 34393797, 2021). "Lung cancer patients treated with EGFR inhibitors inevitably develop resistance, leading to tumor recurrence and mortality." (PMID 34359807, 2021). "We assessed the impact of angiogenesis inhibitor (AI) eligibility on epidermal growth factor receptor mutant non‐small cell lung cancer." (PMID 34587359, 2021). "We found that eRNAs chr12.51786511.51786834 and chr7.55132578.55133258 were located in close proximity to the oncogenes GALNT6 and EGFR, which promote metastasis and invasion of lung cancer cells." (PMID 34439379, 2021). "The optimal sequence for the administration of epidermal growth factor receptor (EGFR) tyrosine kinase inhibitors (TKIs) for treating non‐small cell lung cancer (NSCLC) is still unclear." (PMID 34258882, 2021). "The same group also reported that HNK can induce EGFR degradation by inhibiting HSP90 in lung cancer cells and in subcutaneously implanted mouse models." (PMID 33806040, 2021). "This study examined the safety and tolerability of erlotinib and the heat shock protein 90 inhibitor onalespib in EGFR-mutant non–small cell lung cancer (NSCLC)." (PMID 34140248, 2021). "EGFR can regulate the cycle of lung cancer cells through signal transduction pathways, promote tumor cell proliferation, induce angiogenesis, and promote tumor spread and metastasis." (PMID 33442397, 2021). "In this present work, we have highlighted an induced overexpressed SOX2‐OT level, where siRNAs knockdown of SOX2‐OT reduces total‐ and phosphorylated‐AKT protein levels in EGFR‐wild‐type, KRAS‐mutated A549 lung cancer cells." (PMID 33433063, 2021).
lung cancer (continued). "For our work, we used a panel of nine human and mouse lung cancer cell lines (sensitive or CTD-resistant) with diverse mutational/oncogenic driver profiles (i.e., KRAS G12 mutants, MET amplification, EGFR exon 19 deletion, among others)." (PMID 33850249, 2021). "Previous studies in lung cancer support Sox-2–mediated resistance to EGFR tyrosine kinase inhibitors." (PMID 34546978, 2021). "Because the tumor tissue was found to be positive for the EGFR T790M resistance mutation by bronchoscopy, the EGFR-TKI treatment was changed to osimertinib, decreasing the size of the lung cancer lesions." (PMID 34327032, 2021). "Given the recent understanding of the potential discordance between primary tumors and brain metastasis, the objective of this study was to analyze discordance in EGFR status in patients with lung cancer brain metastasis (LCBM)." (PMID 35201504, 2021). "Despite treatment with various EGFR tyrosine kinase inhibitors, recurrence and metastasis of lung cancer are inevitable." (PMID 34445110, 2021). "Some studies have shown that TMB is negatively associated with clinical outcomes in patients with metastatic EGFR-mutant lung cancer treated with EGFR TKI, including OS38,39." (PMID 34459571, 2021). "Statistical analysis of data from large cohorts has shown that there are high levels of EGFR expression in tissues of at least 10 cancer types, including lung cancers, in comparison with normal tissues." (PMID 33931980, 2021). "Afatinib is an irreversible, second-generation EGFR TKI which has been shown to have better RR, PFS and overall survival (OS) when used in patients of lung cancer harboring susceptible EGFR mutations, compared with platinum-based chemotherapy." (PMID 33941115, 2021). "Among them, KRAS, which is frequently mutated in lung cancer, and EGFR, which is a major therapeutic target in this disease, were also predicted targets of three miRNAs identified in EBC from lung cancer patients." (PMID 33572343, 2021). "This demonstrated that EGFR/MET tumors are resistant to osimertinib, mimicking what is observed in EGFR-mutated lung cancer patients with MET amplification." (PMID 34298655, 2021). "In this study, our results showed that protein stability of the active glucose transporter SGLT1 was dramatically enhanced by EGFR relying on PKCδ-mediated phosphorylation to support glucose uptake and viability of ER lung cancer cells." (PMID 34155348, 2021). "As with EGFR-mutant lung cancer, a remaining question with highly effective ALK inhibitors is when to use them alone versus in combination with radiotherapy for intracranial metastases at diagnosis." (PMID 34859233, 2021). "In lung cancer, curcumin has been shown to downregulate EGFR expression by inducing expression of an E1-like ubiquitin-activating enzyme, UBE1L, which represses EGFR protein expression and promotes EGFR internalization." (PMID 34867402, 2021). "Afatinib (Afb), a chemotherapeutic drug approved for the treatment of EGFR positive lung cancer, has been conjugated with AuNPs, to improving drug efficacy and biocompatibility, administered to in vitro lung cancer cells." (PMID 34104817, 2021). "Further indications of the importance of the subcellular localization of PKCδ to its function was recently demonstrated by a study reporting its role in EGFR TK inhibitor resistance when localized in the nucleus in non–small cell lung cancer." (PMID 33411917, 2021). "The existing dogma dictates that EGFR-mutant and MET-amplified lung cancers codepend on the concurrent activation of both EGFR and a MET kinases for survival, making them unresponsive to single-agent TKI treatment against either receptor." (PMID 34516823, 2021).